PGGT1B (protein geranylgeranyltransferase type I subunit beta)
Description:
Catalyzes the transfer of a geranyl-geranyl moiety from geranyl-geranyl pyrophosphate to a cysteine at the fourth position from the C-terminus of proteins having the C-terminal sequence Cys-aliphatic-aliphatic-X. Known substrates include RAC1, RAC2, RAP1A and RAP1B.
Synonyms: GGTI; BGGI
Tractability: Small molecule: a high-quality ligand is known; it belongs to a druggable protein family. PROTAC: ubiquitination databases record sites on it; its protein half-life has been measured; a small molecule that binds it is known.
Target class: Enzyme; Transferase
Gene: Protein-coding gene on chromosome 5 (115,204,012 to 115,262,877, reverse strand). Ensembl gene ENSG00000164219.
Subcellular location (Human Protein Atlas): Endoplasmic reticulum; Nucleoplasm; Cytosol
Pathways (Reactome):
Immune System: GBP-mediated host defense
Gene Ontology:
Molecular function: protein binding; protein geranylgeranyltransferase activity; CAAX-protein geranylgeranyltransferase activity; zinc ion binding; catalytic activity; protein prenyltransferase activity
Biological process: protein geranylgeranylation; CAAX-box protein maturation
Cellular component: CAAX-protein geranylgeranyltransferase complex; cytosol
Genetic constraint (gnomAD): Loss-of-function variants: 10 observed, 12.34 expected, observed/expected ratio (o/e) 0.81, 90% interval 0.5 to 1.37. The upper end of that interval is the gene's LOEUF score, 1.37, which puts it in group 5 of 6, group 1 being the genes least tolerant of losing a copy. Missense variants: 151 observed, 171.3 expected, observed/expected ratio (o/e) 0.88, 90% interval 0.77 to 1.01. Synonymous variants: 71 observed, 67.66 expected, observed/expected ratio (o/e) 1.05, 90% interval 0.87 to 1.28.
Homologues: Orthologues: chimpanzee PGGT1B (100% identical), macaque PGGT1B (99% identical), pig PGGT1B (98% identical), dog PGGT1B (98% identical), guinea pig PGGT1B (97% identical), mouse Pggt1b (97% identical), rat Pggt1b (86% identical), rabbit PGGT1B (86% identical), tropical clawed frog pggt1b (77% identical), zebrafish pggt1b (63% identical), Drosophila melanogaster betaggt-I (43% identical). Paralogues in human: FNTB (26% identical), RABGGTB (25% identical).
Diseases named in the same sentence as PGGT1B in open-access papers:
PGGT1B is named in the same sentence as 21 diseases in open-access papers, as found by Europe PMC text mining. Sharing a sentence is not in itself a finding about the gene and the disease. The quoted sentences say what the papers report.
psoriasis (2 papers, 2025). An autoimmune condition characterized by red, well-delineated plaques with silvery scales that are usually on the extensor surfaces and scalp. "A possible mechanism for this is that PGGT1B-deficient macrophages migrate to the epidermis more easily during psoriasis, which leads to the activation of Cdc42, NF-κB signaling, and NLRP3 inflammatory corpuscles." (PMID 40430037, 2025). "The proteomic analysis enabled us to identify 17 differentially expressed proteins associated with Pggt1b deficiency in the psoriasis macrophage model (folded change ≥ 1.3 and p < 0.05)." (PMID 40192076, 2025). "In order to study the relationship between PGGT1B deficiency and rash in psoriasis, we used myeloid cell-specific PGGT1B knockout mice as the conditional knockout (cko) group, and wild Pggt1bfl/flLyz2wt/wt mice as the control group (wt group)." (PMID 40430037, 2025). "In this study, it was found that PGGT1B deficiency in myeloid cells aggravates imiquimod-induced psoriasis-like lesions, accompanied by excessive secretion of inflammatory factors." (PMID 40430037, 2025). "The results showed that PGGT1B deficiency in myeloid cells aggravates imiquimod-induced psoriasis-like lesions, accompanied by excessive secretion of inflammatory factors." (PMID 40430037, 2025). "Bone marrow PGGT1B deficiency aggravated the psoriasis-like lesions induced by imiquimod in mice." (PMID 40430037, 2025). "In order to explore the relationship between PGGT1B deficiency and inflammation in psoriasis, we measured the mRNA and cytokine expressions of inflammatory factors IL-1β, IL-6, TNF-α, IL-17A, and IL-10 in the most serious stage of skin injury in mice using Luminex and qRT-PCR." (PMID 40430037, 2025). "In this study, in order to explore the relationship between PGGT1B deficiency and inflammation in psoriasis, we also detected the mRNA and cytokine expressions of inflammatory factors IL-1β, IL-6, TNF-α, IL-17A, and IL-10 in the most serious stage of skin injury in mice." (PMID 40430037, 2025). "The overexpression of these inflammatory factors is one of the important characteristics in the pathogenesis of psoriasis, which is consistent with previous research results showing that the loss of PGGT1B may lead to an imbalance of the immune system, thus aggravating the inflammatory response." (PMID 40430037, 2025). "Psoriasis-like lesions induced by IMQ are aggravated when PGGT1B expression is reduced in mouse bone marrow cells." (PMID 40430037, 2025). "To investigate the effects of myeloid-specific PGGT1B knockout on the development of psoriasis, we stimulated BMDMs with R848 to mimic the immune microenvironment of psoriatic macrophages in mice." (PMID 40430037, 2025). "In summary, this study explored the role and molecular mechanism of PGGT1B in the pathogenesis of psoriasis by establishing myeloid cell-specific PGGT1B gene knockout mice and imiquimod-induced psoriasis mice models." (PMID 40430037, 2025). "The purpose of this study is to explore the role and molecular mechanism of PGGT1B in the development of psoriasis." (PMID 40430037, 2025). "In this study, bone marrow cell-specific PGGT1B knockout mice were constructed using gene knockout technology, which further confirmed the key role of PGGT1B in psoriasis." (PMID 40430037, 2025). "This study aims to explore the role and molecular mechanism of protein geranylgeranyltransferase type I subunit beta (PGGT1B) in the development of psoriasis." (PMID 40430037, 2025). "Psoriasis pathogenesis involves dysregulated immune responses, yet the role of protein prenylation (particularly PGGT1B-mediated geranylgeranylation) in macrophage-driven inflammation remains poorly understood." (PMID 40430037, 2025). "Bone marrow-derived macrophages (BMDMs) from wild-type and PGGT1B knockout mice were cultured and stimulated with resiquimod (R848) to simulate the immune microenvironment of psoriasis." (PMID 40430037, 2025).
psoriasis (continued). "Myeloid cell-specific PGGT1B gene knockout mice were generated, and a mouse psoriasis model was established with imiquimod to study the role and mechanism of PGGT1B gene downregulation-induced macrophage activation in the pathogenesis of psoriasis." (PMID 40430037, 2025). "However, the role of macrophage protein geranylgeranyl transferase type-1β subunit (PGGT1B) in psoriasis is unclear." (PMID 40192076, 2025). "Therefore, future research needs to explore the role of PGGT1B in different cell types and its overall role in the pathogenesis of psoriasis." (PMID 40430037, 2025). "In addition, PGGT1B may indirectly participate in the pathogenesis of psoriasis by affecting the proliferation and differentiation of keratinocytes." (PMID 40430037, 2025). "We established a mouse model of psoriasis induced by imiquimod by constructing myeloid cell-specific PGGT1B gene knockout mice and combined it with RNA-seq analysis to study the role of macrophage activation induced by PGGT1B gene downregulation in the pathogenesis of psoriasis." (PMID 40430037, 2025). "Previous studies have found that the expression of PGGT1B in peripheral blood mononuclear cells of patients with psoriasis decreased significantly, suggesting that this enzyme may be involved in the pathogenesis of psoriasis." (PMID 40430037, 2025). "Our results show that PGGT1B deletion can promote the proliferation and inhibit the differentiation of HaCaT cells, which may be closely related to the pathological characteristics of excessive proliferation and abnormal differentiation of keratinocytes in psoriasis lesions." (PMID 40430037, 2025). "Therefore, future research needs to include human psoriasis skin or PBMC datasets and verify the expression level and function of PGGT1B in patients with psoriasis in clinical samples." (PMID 40430037, 2025). "Reduced PGGT1B levels can increase the expression of CDC42, which further activates NLRP3 inflammation in macrophages through NF-κB signaling, further aggravating the inflammatory state of psoriasis." (PMID 40430037, 2025). "By comparing the performance of wild-type and PGGT1B knockout mice in the psoriasis model, we found that the lack of PGGT1B in bone marrow significantly aggravated the psoriasis-like lesions induced by imiquimod in mice." (PMID 40430037, 2025). "The number of NF-κB nuclear translocations in the cko group was significantly higher than that in the wt group (p < 0.05), indicating that the lack of myeloid PGGT1B aggravated the psoriasis-like inflammation induced by IMQ." (PMID 40430037, 2025).
schizophrenia (2 papers, 2020). A major psychotic disorder characterized by abnormalities in the perception or expression of reality. "Accordingly, we assayed protein expression of the prenyltransferases subunits FNTA, FNTB, PGGT1B, RABGGTA, and RABGGTB in DLPFC from schizophrenia and matched comparison subjects." (PMID 32066669, 2020). "To test this, we assayed protein expression of the five prenyltransferase subunits (FNTA, FNTB, PGGT1B, RABGGTA, and RABGGTB) in postmortem dorsolateral prefrontal cortex from patients with schizophrenia and paired comparison subjects (n = 13 pairs)." (PMID 32066669, 2020). "In summary, we found decreased protein expression of the prenyltransferase subunits FNTA, PGGT1B, and RABGGTB in schizophrenia DLPFC as well as evidence from a bioinformatic analysis of differential gene expression of prenylation-associated genes across multiple brain regions and cortical layers." (PMID 32066669, 2020). "We found decreased levels of FNTA (14%), PGGT1B (13%), and RABGGTB (8%) in schizophrenia." (PMID 32066669, 2020). "We found protein expression of FNTA, PGGT1B, and RABGGTB prenyltransferase subunits decreased in schizophrenia DLPFC relative to paired comparison subjects, changes not likely due to chronic antipsychotic treatment." (PMID 32066669, 2020).
Arthritis (1 paper, 2025). Inflammation of a joint. "Myeloid-specific deletion of Pggt1b, the gene coding for GGTase-I, leads to spontaneous and severe erosive arthritis in mice; however, the underlying mechanisms remained unclear." (PMID 40883609, 2025). "In this study, we demonstrate that arthritis in mice with myeloid-specific Pggt1b deficiency is driven by unprenylated GTP-bound small RHO family GTPases, which in turn trigger Pyrin (Mefv) inflammasome activation, GSDMD-dependent macrophage pyroptosis, and IL-1β secretion." (PMID 40883609, 2025).
childhood cancer (1 paper, 2019). "We propose that PSMB6, PGGT1B, UBQLN2 and UQCR2 are housekeeping genes with low expression in childhood cancer." (PMID 31108950, 2019).
colitis (1 paper, 2023). Inflammation of the colon. "Loss of Pggt1b in the T cells of mice also causes spontaneous colitis via impaired RhoA signaling, and the intestinal T cells of IBD patients have lower Pggt1b level." (PMID 36690621, 2023). "In IBD patients, T cells isolated from gut tissues showed decreased expression of Pggt1b, which led to dysfunction of RhoA in IECs and T cells in mice, promoting CD4 + T cell accumulating at the intestine and aggravating colitis." (PMID 36690621, 2023).
gout (1 paper, 2020). A condition characterized by painful swelling of the joints, which is caused by deposition of urate crystals. "In gout patients, seven aberrant DNA methylation sites that were mapped to seven genes (PGGT1B, INSIG1, ANGPTL2, JNK1, UBAP1, RAPTOR, and CNTN5) and survived genetic and meQTL analyses or causal inference tests were discovered." (PMID 32630231, 2020). "Although some nearby variants were associated with PGGT1B methylation or gout, no variants were concurrently associated with PGGT1B methylation and gout." (PMID 32630231, 2020). "In the context of hypermethylation-decreased transcription, hypermethylated PGGT1B might result in reduced PGGT1B transcription, subsequently augmenting IL-1β production in macrophages and facilitating gout." (PMID 32630231, 2020). "Thus, a common variant did not underlie the observed epigenetic associations between PGGT1B methylation and gout." (PMID 32630231, 2020). "In conclusion, this study provided evidence of aberrant methylation changes of PGGT1B, INSIG1, ANGPTL2, JNK1, UBAP1, RAPTOR, and CNTN5 in gout." (PMID 32630231, 2020). "Six (PGGT1B, INSIG1, ANGPTL2, JNK1, UBAP1, and RAPTOR) were novel genes in the field of gout." (PMID 32630231, 2020). "Given the roles of PGGT1B, INSIG1, ANGPTL2, JNK1, UBAP1, RAPTOR, and CNTN5 in regulating IL-1β or gouty inflammation and differential methylation of these genes in gout, the next important topic is the consequence of manipulating the respective signaling pathways." (PMID 32630231, 2020). "Moreover, measuring transcription factors identified in this study and chromatin immunoprecipitation (ChIP) for these transcription factors would provide more clues about the mechanistic link between PGGT1B, INSIG1, ANGPTL2, JNK1, UBAP1, RAPTOR, and CNTN5 methylation and gout." (PMID 32630231, 2020). "If common genetic variation did not contribute to the epigenetic associations of PGGT1B, INSIG1, ANGPTL2, JNK1, and CNTN5 with gout, it would be interesting to clarify mechanisms underlying the differential methylation of these CpG sites in gout." (PMID 32630231, 2020). "Taken together, these results suggested that relationships between PGGT1B, INSIG1, ANGPTL2, JNK1, UBAP1, RAPTOR, and CNTN5 methylation and gout were not confounded by genetic mediators." (PMID 32630231, 2020).
cancer (6 papers, 2006 to 2026). A tumor composed of atypical neoplastic, often pleomorphic cells that invade other tissues. "This was prominently seen in PGGT1B in Caki-1 cells, raising the possibility that DNA methylation is involved in the dysregulation of PTase expression in cancer." (PMID 41892366, 2026).
PGGT1B also shares sentences with these, for which no sentence is quoted: tumor (7 papers); bladder cancer (2); ovarian carcinoma (2); atherosclerosis (1); breast carcinoma (1); diabetes (1); hepatocellular carcinoma (1); hyperuricemia (1); immune diseases (1); lung carcinoma (1); lymphopenia (1); melanoma (1); pancreatic cancer (1); Psoriasiform dermatitis (1).